ICAM5 (intercellular adhesion molecule 5)
Description:
Cell adhesion molecule that functions as a receptor ligand of the signaling receptor ITGAL:ITGB2/LFA-1 (lymphocyte-function associated (LFA) molecule 1) ensuring neuron cell-leukocyte adhesion. Creates homophilic cell adhesion promoting dendritogenesis and arborization of hippocampal neurons.
Synonyms: TLCN; TLN
Tractability: Antibody: its Gene Ontology location is reachable by antibodies, with high confidence; UniProt predicts a signal peptide or a membrane-spanning region. PROTAC: its protein half-life has been measured.
Gene: Protein-coding gene on chromosome 19 (10,289,952 to 10,296,778, forward strand). Ensembl gene ENSG00000105376.
Subcellular location: Cell membrane; Cell projection; Cell projection, uropodium; Cell projection, dendritic spine membrane
Pathways (Reactome):
Extracellular matrix organization: Integrin cell surface interactions
Immune System: Immunoregulatory interactions between a Lymphoid and a non-Lymphoid cell
Gene Ontology:
Molecular function: protein binding; integrin binding; receptor ligand activity
Biological process: cell-cell adhesion mediated by integrin; homophilic cell-cell adhesion; protein homotetramerization; cell adhesion; neuron cell-cell adhesion; cell-cell adhesion; regulation of synapse assembly; signal transduction
Cellular component: cell projection; uropod membrane; dendritic spine membrane; plasma membrane; glutamatergic synapse; membrane; postsynapse; uropod
Genetic constraint (gnomAD): Loss-of-function variants: 39 observed, 75.71 expected, observed/expected ratio (o/e) 0.52, 90% interval 0.4 to 0.67. The upper end of that interval is the gene's LOEUF score, 0.67, which puts it in group 2 of 6, group 1 being the genes least tolerant of losing a copy. Missense variants: 1,054 observed, 1,260.1 expected, observed/expected ratio (o/e) 0.84, 90% interval 0.79 to 0.88. Synonymous variants: 539 observed, 575.19 expected, observed/expected ratio (o/e) 0.94, 90% interval 0.87 to 1.01.
Homologues: Orthologues: chimpanzee ICAM5 (99% identical), macaque ICAM5 (98% identical), dog ICAM5 (89% identical), pig ICAM5 (89% identical), rat Icam5 (85% identical), mouse Icam5 (85% identical), guinea pig ICAM5 (83% identical). Paralogues in human: ICAM3 (29% identical), ICAM1 (26% identical), ICAM2 (9% identical), ICAM4 (8% identical).